TNF (tumor necrosis factor)
Diseases named in the same sentence as TNF in open-access papers (continued):
Sharing a sentence is not in itself a finding about the gene and the disease.
Sepsis (continued). "Sepsis is primarily caused by overactivation of the immune system leading to the production of inflammatory cytokines including interleukins and tumor necrosis factor (TNF)." (PMID 33679637, 2021). "In addition, the high levels of PCT, a marker for sepsis in humans and mice, support that TNF induced a systemic inflammation and also show that the pathophysiological response to TNF is similar to that caused by infection." (PMID 32410851, 2020). "Consequently, susceptibility towards sepsis reduced dramatically as evidenced by improved survival index and attenuated levels of TNF-α, a signature pro-inflammatory cytokine, following LPS challenge." (PMID 31980623, 2020). "TNF-α +489G/A A-allele carriage was associated with significantly lower risk of developing sepsis and sepsis shock (AA+AG vs GG: OR = 0.53; p = 0.004; 95% CI = 0.34–0.82 and OR = 0.39; p = 0.003; 95% CI = 0.21–0.74, respectively) but not with sepsis-related outcomes." (PMID 32171247, 2020). "TNF-α and IL-6 are the primary mediators of sepsis, which can cause septic shock." (PMID 33042031, 2020). "Indeed, systemic administration of TNF causes symptoms and injury typically associated with sepsis, such as pulmonary, renal and gastrointestinal inflammation, hemorrhagic lesions and necrosis." (PMID 32027657, 2020). "For example, in a mouse model of Streptococcus pneumoniae sepsis, pre-treatment with oral antibiotics prior to sepsis onset was associated with lower levels of lung TNF-α, a pro-inflammatory cytokine, whereas others have shown the opposite effect of gut microbiome depletion on TNF-α." (PMID 32487252, 2020). "In sepsis, a single module associated with TNF-α/P3C/PGE2 (TPP) was significantly enriched." (PMID 31906585, 2020). "We recently published the results of a single-center, prospective immune phenotyping study of 102 children with severe sepsis/septic shock in which the use of hydrocortisone and severe reduction in the TNFα response were both associated with longer durations of MODS." (PMID 32887651, 2020). "For example, HOTAIR promotes TNF-α expression and aggravates myocardial damage caused by sepsis." (PMID 33204219, 2020). "Specifically, increased TNF in sepsis may be associated with increased EC F3 expression and TF production, as well as down-regulation of THBD and PROCR, resulting in decreased APC generation for suppression of FVIII and FV inactivation." (PMID 32029851, 2020). "We therefore tested the hypothesis that injection of TNF-α provokes specific changes in the exhalome of rats that might be diagnostic for sepsis and inflammation." (PMID 32549262, 2020). "It has been shown that a low level of HDL-C negatively correlates with the severity of sepsis and is associated with a massive release of inflammatory mediators (i.e., tumor necrosis factor α (TNF-α), interleukin 1β (IL-1β), interleukin 6 (IL-6), and interleukin 8 (IL-8))." (PMID 33228032, 2020). "It was found that miR-19b-3p level was negatively associated with serum levels of both IL-6 (r = − 0.852, P < 0.001) and TNF-α (r = − 0.761, P < 0.001), revealing that miR-19b-3p might be associated with inflammatory responses for sepsis patients." (PMID 32188465, 2020). "The nanocomposite inhibited macrophage activation-related inactive rhomboid protein 2/TNF-α converting enzyme/TNF-α signaling and restored nuclear factor erythroid-2-related factor 2 to relieve Listeria monocytogenes-induced metabolic disorder and septicemia-associated systemic inflammation." (PMID 34138224, 2020). "Engagement issues included self‐cessation of medications, hesitancy to up‐titrate therapies, and—in one instance—declining colorectal surgical input for severe perianal disease and thus rendering the patient ineligible for anti‐TNF therapy (due to the sepsis risk)." (PMID 31832552, 2019). "A possible explanation for the failure of TNF inhibitors in sepsis might be linked to the TNFR2 inhibition." (PMID 31787972, 2019).
Sepsis (continued). "In accordance with organ dysfunction in the FtHfl/fl mice, 24 h after CLP surgery, there was a significant increase in the levels of cytokines that have been implicated in the pathogenesis of sepsis, including the pro-inflammatory cytokines, TNF-α, IFN-γ, IL-6, IL-12, CXCL1, IL-1β, and IL-2." (PMID 30804939, 2019). "Sepsis-induced organ damage is caused by an aberrant increase in inflammatory mediators, e.g., nitric oxide (NO), pro-inflammatory cytokines (e.g., interleukin (IL)-1β and tumor necrosis factor (TNF)-α), and glutamate." (PMID 31847346, 2019). "Since CD14dim/CD16pos/CD45pos cells are the monocyte subpopulation providing most of the TNFα production, the low cell count of patrolling monocytes on the third day in nonsurvivors could be associated with the immunosuppression of sepsis." (PMID 29499723, 2018). "In contrast, it has been reported that male rats display an early suppressive immune response (decreased levels of TNF-α as compared with females) after LPS injection that is testosterone dependent, confirming an increased susceptibility to sepsis in males as compared with females." (PMID 29925409, 2018). "The results of an in vitro (lipopolysaccharide (LPS))-stimulated experiment showed that this sepsis-associated high-risk AA genotype significantly increased IL-27 levels and enhanced TNF-α and IL-1β production in the peripheral blood mononuclear cells (PBMCs) upon exposure to LPS in vitro." (PMID 30268141, 2018). "Furthermore, sepsis-associated pro-inflammatory cytokines, such as TNF-α, induce activation of SMPD1 and, subsequently, the formation of ceramide in primary isolated hepatocytes." (PMID 30326559, 2018). "It is characterized by sustained excessive inflammation and immune suppression, and many studies have shown that TNF is the master mediator of the inflammatory response seen in sepsis and shock, the life-threatening condition caused by circulatory and/or metabolic abnormalities." (PMID 29751683, 2018). "Trauma and sepsis cause tissue injury, resulting in the release of DAMPs that are able to induce a pro-inflammatory signal cascade and the release of pro-inflammatory cytokines such as TNF-α." (PMID 29616016, 2018). "Recent data have suggested that stimulation of primed macrophages with purified M proteins may promote inflammasome activation and secretion of IL-1β, which together with IL-6 and TNFα is implicated as a key mediator of sepsis." (PMID 29579113, 2018). "Notably, the in vitro LPS-stimulated experiment showed that the sepsis-associated AA risk genotype significantly increased TNF-α and IL-6 secretion in PBMCs upon exposure to LPS in vitro." (PMID 30268141, 2018). "We found that TNF-α rs1800629 was associated with increased sepsis risk in the overall population in four genetic models, including A vs. G (P<0.001, odds ratio (OR)=1.32), GA vs. GG (P<0.001, OR=1.46), GA+AA vs. GG (P<0.001, OR=1.46), and carrier A vs. carrier G (P<0.001, OR=1.32)." (PMID 29340067, 2017). "Likewise, the coma that is often part of an encephalopathy accompanying sepsis, influenza or malaria can also be rationalized in cytokine terms, with associated coma argued to arise through increased cerebral TNF reducing orexin levels." (PMID 28451786, 2017). "Various gene polymorphisms have been proved to be linked with the development of SS and severe sepsis, such as the tumor necrosis factor (TNF) gene, but some may also be associated with the increased mortality rate in SS patients like the ADRB2 gene." (PMID 28336767, 2017). "However, increases in IL-6, IL-8 and TNFα are also associated with a wide variety of immune activity like acute-phase response (e.g. sepsis and viral infections) and autoimmunity which also can be related to schizophrenia." (PMID 28923068, 2017). "This may reduce the statistical power for identifying possible associations between TNF-α −308 A/G polymorphism and sepsis, especially septic shock, for which the meta-analysis included only 8 studies." (PMID 29212277, 2017).
Sepsis (continued). "However, TNF-α rs1800629 was also negatively correlated with sepsis susceptibility in preterm infants in Germany and low-birth-weight infants in Hungary." (PMID 29340067, 2017). "We aimed to determine whether changes in mRNA expression of HLA-DR are associated with impaired TNFα response in human sepsis." (PMID 28771573, 2017). "Associations between TNF-α SNPs and sepsis risk are still uncertain." (PMID 29340067, 2017). "Further research should examine the possibility of ethnic bias in the associations of sepsis risk with certain alleles/genotypes at the −308 A/G polymorphism in the TNF-α gene, with certain alleles/genotypes at other SNPs in the TNF-α gene, and with SNPs in other genes." (PMID 29212277, 2017). "Our analysis focused on the genetic relationship between sepsis risk and the rs1800629 and rs361525 polymorphisms within the TNF-α promoter region, in that sufficient data was only obtained for the meta-analysis of rs1800629, rs361525 polymorphisms, after our data extraction." (PMID 29340067, 2017). "The activation of macrophages by the stimulation of the TLR4 ligand leads to the production of several inflammatory mediators, including TNF, IL-1β and IL-6, that contribute to the inflammatory response to defend pathogenic infection, but also associate with the severity of sepsis." (PMID 28593998, 2017). "Moreover, for over a decade, it has consistently been demonstrated in whole blood that decreased TNFα production induced by endotoxin or lipopolysaccharide (LPS) is associated with higher morbidity and mortality in sepsis patients." (PMID 28771573, 2017). "TNF-α and IL-1β are major mediators causing myocardial dysfunction in sepsis." (PMID 28270914, 2017). "Our meta-analysis suggests that future research on risk factors of sepsis-related mortality may wish to focus on other SNPs in the TNF-α gene or on SNPs in other cytokine genes." (PMID 29212277, 2017). "In this study, we hypothesize that the mRNA expression level of HLA-DRA, measured by qPCR, is significantly associated with LPS-induced TNFα production in whole blood from patients with sepsis or septic shock." (PMID 28771573, 2017). "We investigated the hypothesis based on cytokine imbalance because sepsis-induced immunosuppression is associated with decreased production of inflammatory cytokines and a high IL-10-to-TNF ratio." (PMID 27441846, 2016). "In addition, CSE gene deletion not only attenuated sepsis associated activation of ERK1/2-NF-κB p65 signalling but also abolished the generation of cytokines TNF-α, IL-6, and IL-1β and chemokines MCP-1 and MIP-2α." (PMID 27518439, 2016). "Many forms of systemic inflammation, including sepsis, are associated with proteinuria with high levels of pro-inflammatory cytokines such as IL-1, IL-6 and TNFα, and some cases of NS have been shown to be responsive to TNFα blockade." (PMID 27125280, 2016). "In our study, the rs10865710 polymorphism in the PPARγ gene could affect TNFα production and was associated with the development of sepsis and MODS in Chinese Han trauma patients." (PMID 27023591, 2016). "Furthermore, compared to the inflammatory response typically related to exercise, severe inflammation (e.g., sepsis) has been associated with a distinctively different cascade of cytokines in the circulation (i.e., TNF-α, IL-1β and IL-6 in that order)." (PMID 26378783, 2015). "In conclusion, our study demonstrates that the alternations in the genotype and allele frequency of IL-1β (−511C/T), TNF-α (−308G/A), TNF-α (−238G/A) and IL-10(−1082G/A) genes are associated with an increased risk of sepsis development in major trauma patients and outcomes." (PMID 26561011, 2015). "Patients having heterozygous for the allele TNF-308 G/A had a lower risk of developing sepsis." (PMID 26561011, 2015). "In other words degree of TNF-α in sepsis patients is associated with the production of IL-10." (PMID 26561011, 2015).
Sepsis (continued). "Moreover, TNF-α is a potent mediator of the shock-like state associated with thermal injury and sepsis." (PMID 26273138, 2015). "Currently, vast evidence indicates that certain functional genetic variants, such as those in the genes of TNF-a, IL-6 and other inflammatory-related proteins, may be associated with the susceptibility to sepsis by influencing its inflammatory pathogenesis." (PMID 25888255, 2015). "We have demonstrated that the rs842647 polymorphism affects TNF-α production and might be used to estimate risk for sepsis and MODS in trauma patients." (PMID 25880845, 2015). "Sequence-specific primer based PCR indicated that eight polymorphic loci IL-1α /-889, IL-1β/-511, IL-1R (pstI 1970), TGF-β/ code 10, TNF-α/-308, TNF-α/-238, IL-6/+565 and IL-10/-1082, out of 22 SNPs are significantly associated with sepsis morbidity and outcome." (PMID 26561011, 2015). "MAP3K8 is linked to sepsis in mice, with being crucial for the TNF production." (PMID 25814982, 2015). "In sepsis, the actions of inflammatory cytokines such as tumor necrosis factor (TNF) and interleukin-1 (IL-1) cause production of large amounts of tissue factor (TF) from monocytes/macrophages and the vascular endothelium, thus leading to marked coagulation activation." (PMID 25520834, 2014). "The protection of female hearts against the dysfunction associated with sepsis is (at least in part) attributable to cardiac activation of the Akt/eNOS survival pathway, decreased activation of NF-κB, and decreased expression of iNOS, TNF-α and IL-6." (PMID 24945834, 2014). "As sepsis in patients was associated with elevated levels of TNF-α and interleukins (IL)-1, as well as IL-6 in cerebrospinal fluid, the pathophysiological mechanisms of SAE may be the result of a cascade of neuroinflammatory processes as followed." (PMID 25722876, 2014). "In the 1990s, sepsis was believed to be associated with an exacerbated release of mainly proinflammatory cytokines, such as tumor necrosis factor (TNF-α), interleukin (IL-1, IL-6, and IL-12), interferon-γ (IFN-γ), and macrophage migration inhibitory factor (MIF)." (PMID 25614712, 2014). "Since high iNOS expression/protein and •NO activity in the sepsis literature are associated with high TNF-α, IL-6, and ensuing toxicity, we evaluated how HOCbl might impact upon systemic levels of TNF-α and IL-6 triggered by LPS." (PMID 23781123, 2013). "TNF-α is a peptide mainly derived from stimulated macrophages and is implicated in the pathogenesis of multiple organ system and cell impairment associated with sepsis." (PMID 24058571, 2013). "The pathogenesis of sepsis-induced mitochondrial injury is associated with free radical generation and the release of a variety of exacerbating inflammatory mediators (e.g. TNF-α, IL-1β and IL-6) which directly or indirectly influence mitochondrial function and energy production." (PMID 24039949, 2013). "Since we hypothesized that both AKI and ALI would occur at a similar time point after the onset of sepsis due to TNF-α-associated SIRS response, we sought to determine the onset of this proinflammatory response." (PMID 24265742, 2013). "TNF-α, a primary and potent mediator of inflammation, plays a critical role in the inflammatory response and is capable of causing end-organ dysfunction that occurs in severe sepsis." (PMID 23840548, 2013). "LPS−activated macrophages release proinflammatory cytokines such as TNF-α and IL-6, which could cause inflammatory disorders, sepsis or other liver injuries." (PMID 24143247, 2013). "In addition, this mutation had been associated to occurrence of severe sepsis through important secretion of important amounts of pro-inflammatory cytokines (TNFα and IL-6)." (PMID 24252506, 2013). "Endogenous inflammatory mediators such as TNF-alpha and NO activate premature apoptosis of immune effector cells, which may contribute to the sepsis-associated MODS after severe trauma." (PMID 24371374, 2013).
Sepsis (continued). "Disturbed lymphocyte function is a recognized hallmark feature of sepsis; our results suggest that these in part may be mediated by TNFα-mediated signaling." (PMID 24236088, 2013). "The association between rs1800629 and severe sepsis risk may be explained by its influence on the expression of TNF-α." (PMID 23029405, 2012). "Furthermore, we investigated the association between the genotypes of the TNF gene SNP rs1800629 and TNF-α concentration in culture supernatants of LPS simulated PBMCs obtained from healthy donors and in serum from severe sepsis patients." (PMID 23029405, 2012). "Sepsis is associated with the production of many inflammatory mediators, including TNFα." (PMID 22564340, 2012). "However, there is ample evidence for a causal relationship between free hemoglobin and outcome of sepsis in animal models: free hemoglobin affects Toll-like receptor signal transduction, TNFα generation and mortality." (PMID 22800762, 2012). "In conclusion, our relatively large scale association study demonstrated that individuals with a functional variant in the promoter region of TNF may confer susceptibility to severe sepsis." (PMID 23029405, 2012). "We demonstrate that rs1800625 polymorphism is shown to affect TNFα production, and might be used as a relevant risk estimate for sepsis and MODS in trauma patients." (PMID 22827914, 2012). "Therefore a protein-microarray for point-of-care testing that simultaneously quantifies the sepsis associated serum proteins IL-6, IL-8, IL-10, TNF alpha, S-100, PCT, E-Selectin, CRP and Neopterin has been developed." (PMID 22438722, 2012). "While the same reasons as above for the physiologic CD-56 ratio in our WD-TBI group may be discussed, in the CO-TX group one more aspect needs consideration: raised TNFα levels in a murine sepsis model were associated with an increased ratio of NK cells." (PMID 22529516, 2012). "In a less severe sepsis model, Trif-deficient mice have reduced cytokine production including TNFα, IL-6, and IL-10 suggesting Trif signaling may contribute to systemic inflammation in a mild form of animal sepsis." (PMID 21977329, 2011). "Accumulating evidence underlines the relationship between sepsis, systemic multiorgan damage (lung, liver, kidney, and heart) and elevated serum and peritoneal concentrations of cytokines (IL-1, IL-6, IL-8, IL-10) and tumor necrosis factor (TNF)." (PMID 20015376, 2009). "TNF-α and IL-1 are proinflammatory cytokines that are elaborated by monocytes or macrophages and play pivotal roles in the development of organ dysfunction associated with sepsis." (PMID 18601748, 2008). "Cytokines of particular interest include interleukin-6 (IL-6), tumor necrosis factor-alpha (TNF-α), interleukin-8 (IL-8), and interleukin-10 (IL-10), each having been linked to mortality in conditions such as acute cardiac events, renal failure, sepsis, ARDS, and notably COVID-19." (PMID 40843708, 2025). "Collectively, these findings underscore that thiol–disulfide homeostasis is intricately linked with both classical (CRP, TNF-α) and emerging (IL-40) inflammatory markers, positioning it as a critical integrative biomarker at the intersection of oxidative and inflammatory cascades in sepsis." (PMID 41196905, 2025). "Elevated levels of TNF-α may be associated with inflammatory diseases, sepsis, and cancer." (PMID 40955326, 2025). "However, acute systemic TNF- release causes sepsis and shock." (PMID 38266537, 2024). "Consequently, ICAM-1 regulated via TNF-α could be a possible cause of the alteration in fenestra numbers and gap formation in LSECs, resulting in liver injury during sepsis." (PMID 38254684, 2024). "During sepsis, the pathogen-associated molecular patterns trigger systemic inflammatory responses, leading to an excess production of proinflammatory cytokines that are responsible for coagulopathy, such as interleukin IL-1β, IL-6, and tumor necrosis factor-α (TNF-α)." (PMID 37219401, 2023).